MMP2 (matrix metallopeptidase 2)
Diseases named in the same sentence as MMP2 in open-access papers (continued):
Sharing a sentence is not in itself a finding about the gene and the disease.
melanoma (continued). "Combined effects of increased C4S, CSPG4, and MMP2 increased the invasiveness of the melanoma cells, and therapy with recombinant ARSB may inhibit melanoma progression." (PMID 27926479, 2017). "We next examined MMP-2 activity in WM115 and WM266.4 melanoma cells by gelatin zymography." (PMID 28107182, 2017). "Similarly, BRAF V600E melanoma patients concurrent with LKB1 low expression are more likely to have lymph node metastases and related to the MMP-2 high expression." (PMID 29371951, 2017). "In addition to the observed effects on mRNA expression of CSPG4 and pro-MMP2, the expression of another gelatinase, MMP9, was also increased in the malignant melanoma cells and following silencing of ARSB." (PMID 27926479, 2017). "Therefore, in addition to DPI, we determined the effect of honokiol and NAC on the levels of MMP-2 and MMP-9 in melanoma cells." (PMID 26760964, 2016). "Another group showed that VEGF, IL-6 and MMP-2 proteins were present in the culture supernatants of human melanoma cells with no direct evidence of VEGF detection in their derived exosomes." (PMID 27760548, 2016). "In our study, we found that ING4 significantly reduced the mRNA and protein expressions of MMP-2 and COX-2, which was consistent with the findings in melanoma, osteosarcoma and brain cancer, and the expression of nuclear Sp1 and subsequent DNA binding activity." (PMID 27806345, 2016). "The aim of this study was to evaluate clinical utility of vascular endothelial growth factor (VEGF), matrix metalloproteinase 2 (MMP-2), MMP-9, tissue inhibitors of metalloproteinase 1 (TIMP-1), and YKL-40 in serum of melanoma patients at pathological stages I–III." (PMID 26002577, 2015). "Based on comparison of multiple markers in the same database, we further found the prognostic value of MMP2 to be specific to thick primary melanomas (Stage II), whereas for Stage I, its value was not apparent." (PMID 25784655, 2015). "Specifically, data suggest that MMP2 and MMP9 could be directly involved in BBB permeability and that brain invasion by melanoma cells could be related to the overexpression of many MMPs." (PMID 25692137, 2015). "Therefore, the present study further examined the correlation between NRP1 and MMP2 expression in melanoma biopsies, and analyzed the combined effect of NRP1 and MMP2 expression in predicting patient outcomes." (PMID 25954957, 2015). "Using the same set of melanoma tissue microarrays, we found that BRAF expression and MMP2 expression are the best markers for AJCC Stages I and II, respectively, whereas p27 cytoplasm expression is a superior prognostic marker for patients in both Stages III and IV." (PMID 25784655, 2015). "In addition, the correlation between matrix metalloproteinase 2 (MMP2) and NRP1 expression in patients with melanoma was analyzed." (PMID 25954957, 2015). "Six previously reported independent melanoma biomarkers, including BRAF, MMP2." (PMID 25784655, 2015). "Here we show that, in melanoma cells with low endogenous WNT5A expression, the stimulation with rWNT5A induces a rapid release of exosomes containing the immunomodulatory cytokine IL-6 and the pro-angiogenic factors IL-8, VEGF and MMP2." (PMID 24766647, 2014). "A recent study using tissue microarray and immunohistochemistry of melanoma biopsies of primary and metastatic lesions as well as nevi concluded that MMP-2 expression is a prognostic indicator in primary but not metastatic lesions." (PMID 24069584, 2013). "In melanoma tissue sections, in situ zymography revealed MT1-MMP and secreted MMP-2 accumulate at the invasive front of melanoma cells, and the presence of functionally active MMP-2 is restricted to this region." (PMID 24069584, 2013). "Additionally, CREB is known to play essential roles in regulating MMP2 and MMP9 expression in melanoma and pancreatic cancer cells." (PMID 24113161, 2013).
melanoma (continued). "Interestingly, although MMP-2 and MMP-9 act on similar substrates, and are both expressed in melanoma, MMP-2 appears to be the better prognostic indicator." (PMID 24069584, 2013). "We treated the human A375 melanoma cells with different concentration of GM6001, and we found that the cell adhesion was efficiently inhibited by GM6001 at concentration of 0.5 nM, implying an inhibition on MMP-2 as reported." (PMID 22848537, 2012). "Furthermore, decreased expression of MMP-2 is a key reason for suppression of tumor cell invasion and metastasis following silencing of STAT-3 expression in human melanoma." (PMID 21991388, 2011). "It was also shown that αVβ3 integrins on CS-1 melanoma cells promotes collagenolytic activity that can be blocked using recombinant PEX domain, indicating that addition of PEX to αVβ3 expressing cells prevents binding of MMP-2 to the cell surface." (PMID 22267953, 2011). "Treatment with prothrombin kringle-2 decreased expression of MMP-2 and MMP-9 in the bronchiolar epithelial cells, pneumocytes, endothelial cells, and metastatic tumor cells of B16F10 melanoma, suggesting the possible mechanism of prothrombin kringle-2 antitumor actions." (PMID 22267953, 2011). "DNE3 inhibited the motility and invasion of A2058 cell lines, and DNE3 clearly inhibited the secretion of MMP-2, MMP-9, and u-PA, thus indicating that DNE3 might have anti-invasive properties against a broad spectrum of melanoma cells." (PMID 21274459, 2011). "The observed increase in MMP2 and MMP9 activity as well as other alterations in extracellular matrix and adhesion molecule expression suggested that BRG1 plays an important role in regulating melanoma invasiveness." (PMID 20969766, 2010). "To determine the mechanism by which BRG1 activates MMP2 expression in SK-MEL5 melanoma cells, we investigated whether BRG1 intereacts with a transcriptional regulator of MMP2." (PMID 20969766, 2010). "Nevertheless, the MMP-2 epitope was found to be cross-presented exclusively by melanoma cells and not presented by the endogenous pathway." (PMID 20689590, 2010). "Additionally, some of the genes regulated by AP-2α in melanoma, such as MCAM/MUC18 and MMP-2, are also regulated by the CREB transcription factor." (PMID 20805990, 2010). "However, the mechanism responsible for selective inhibition of MMP-2, MMP-9 and TNF-α expression in HB-19 treated melanoma cells and tumors remains to be elucidated." (PMID 20573279, 2010). "In melanoma, inactivation of CREB by dominant-negative KCREB reduced tumor growth and experimental lung metastasis by acting as a survival factor and regulating the expression and activity of MMP-2 and the adhesion molecule MCAM/MUC18." (PMID 20805990, 2010). "Transfection of plasmids encoding the four mutated forms of MMP-2 (MMP-2C60A, MMP-2C65A, MMP-2C60/65A and MMP-2C233A) into the M117 melanoma cell line or the non-small cell lung carcinoma (NSCLC) 1355 cell line, induced activation of the MMP-2- specific CTL clone." (PMID 20689590, 2010). "This study does not provide strong evidence for further investigation of MMP2 and MMP3 genetic variants in melanoma progression." (PMID 17958893, 2007). "Consequently, targeting MMP-2 and MMP-9 may offer therapeutic potential for inhibiting EMT and metastasis in melanoma The MMP-9’s enzymatic breakdown of ECM barriers modulates the tumor microenvironment to facilitate metastasis." (PMID 41394861, 2025). "Moreover, in such a framework of generalized melanoma cell invasiveness, MMP2 does not contribute to the initial breakdown of brain endothelial barrier." (PMID 38775220, 2024). "Additionally, studies have shown that DNJ extracted from mulberry trees has the potential to impede the spread of B16F10 melanoma cells by potentially reducing MMP-2/9 activity and presence, increasing MMP-2 mRNA expression, and alternating cell surface binding properties." (PMID 38791372, 2024).
melanoma (continued). "In addition, downregulated expression of MMP-2 and MMP-9 with concomitant increased expression of tissue inhibitors of metalloproteinases TIMP-1 and TIMP-2 has also been observed in the luteolin-treated A375 melanoma cells." (PMID 37687080, 2023). "This gene in particular has been suggested as a prognostic biomarker, as patients with strong expression levels had significantly poorer survival compared to those with negative-to-moderate MMP2 expression in a study conducted on tumor samples representing various stages of melanoma progression." (PMID 37047539, 2023). "In the melanoma, hinokitiol could suppress the expression of heparanase through lowering the phosphorylation of protein kinase B (Akt) and ERK, inhibiting the expression and activity of MMP-2/9 simultaneously." (PMID 37560476, 2023). "Furthermore, in a melanoma immunotherapy cohort study, patients who respond to immunotherapy had significantly lower MMP2 expression than patients who did not respond." (PMID 36788565, 2023). "The pharmaceutical actions of Rg3 on the inhibition of MMPs were: MMP2 in six cell lines (originated from lung, thyroid, nasopharynx, colorectum, and bone tumor), MMP9 in four cell lines (lung, thyroid, nasopharynx, and bone tumor), and MMP13 in the B16F10 melanoma cell line, respectively." (PMID 36012338, 2022). "In addition, the combined expression of JWA and ILK could better predict the prognosis of melanoma, and the combined expression of JWA and MMP2 in gastric cancer could also better predict the prognosis of gastric cancer." (PMID 36230577, 2022). "In murine melanoma B16F10 cells, the 70% ethanol extract of A. dahurica root (100 and 200 μg/ml for 24 h) was confirmed to inhibit the growth, migration, invasion and colony formation, while stimulating cell apoptosis via reducing the activity of matrix metalloproteinase-2 (MMP-2) and MMP-9." (PMID 35847034, 2022). "In addition to MMP-2, CAFs secrete other proteolytic enzymes, including MMP-1, MMP-13, and MMP-14, which sustain melanoma invasion by leading to ECM digestion and formation of “tracks”, that melanoma cells use to move through the tumor mass and eventually leave the primary site." (PMID 34067929, 2021). "Furthermore, to test whether SB-3CT have any activity in the context of KD of MMP2 or MMP9, we treated melanoma cell lines (SK-MEL-28 and A375) transfected with shMMP2, shMMP9, or shNC with SB-3CT." (PMID 32988398, 2020). "More specifically, LCL-PLP exerted suppressive actions on the production of MMP-2 (25% reduction of the zymogen form of MMP-2 (p < 0.0001) and 55% reduction of the active form (p < 0.001)) while LCL-DOX doubled the levels of the zymogen as well as the active form of MMP-2 in melanoma in vivo." (PMID 32340166, 2020). "Since we showed a greater inhibitory effect of the FB/SFN combination on cell migration in the metastatic WM266-4 cell line, we evaluated if SFN and FB could alter the production of collagenase MMP-1, gelatinases MMP-2 and MMP-9 and stromelysin MMP-3 in this melanoma cell line." (PMID 32486135, 2020). "Notably, as inhibitor of MMP-2 activity in tumor tissue, PLP encapsulated in LCL overcame the protumor action of DOX when they were administered as combined liposomal drug therapy in B16.F10 melanoma-bearing mice." (PMID 32340166, 2020). "Likewise, zymography analysis of the conditioned media of the cells revealed a relevant decrease of active MMP2 in response to mTORC2 inhibition in melanoma cells in non-degrading gelatin gels." (PMID 33375117, 2020). "Although we could not detect spontaneous brain and lung metastases in our model, our results show that activity of MMP-2 and MMP-9 and angiogenesis were decreased in tumors developed in TNFR1 KO mice, suggestive of a pro-tumoral role of TNFR1 in melanoma progression." (PMID 33202705, 2020).
melanoma (continued). "In addition, the combination of J-4 and Celecoxib could induce MET and decrease the expression of MMP-2/MMP-9 in melanoma cells, which in turn inhibit the migration and invasion of melanoma cells." (PMID 28865485, 2017). "Moreover, acidity-induced experimental pulmonary metastasis was inhibited by treatment with the general MMP inhibitor GM6001 and the general cysteine proteinase inhibitor E-64, suggesting that MMP-2 and MMP-9 are required for the development of pulmonary metastases in our melanoma models." (PMID 26667022, 2015). "The present study suggested EGCG at nontoxic levels could inhibit migration of melanoma cells via downregulation of activities of secreted MMP-2 through the inhibition of the ERK1/2 phosphorylation." (PMID 25184134, 2014). "Here we show, that malignant melanoma cell lines treated with recombinant (r)WNT5A induces a prominent, immediate release of immunomodulatory and pro-angiogenic factors IL-6, IL-8, VEGF and MMP2, while transcriptional activation of these genes remained unaffected." (PMID 24766647, 2014). "Moreover, αvβ3 dependent melanoma cell adhesion preferentially occurs on fibronectin fragments cleaved by MMP-2 rather than on intact fibronectin, and fibronectin fragments appear to promote αvβ3 recruitment into the invasive front of melanoma cells." (PMID 24069584, 2013). "However, no study is available on whether MMP2 functions as an immunosuppressive biomarker in melanoma." (PMID 36788565, 2023). "However, the dysregulation of MMP2 was not correlated to melanoma." (PMID 33679872, 2020). "In addition, cordycepin was able to decrease the expression of MMP-2, MMP-9 and CD44 and suppress cell motility, suggesting that cordycepin not only regulates early stages of melanoma metastasis, but also late stages of melanoma dissemination, such as adhesion and extravasation." (PMID 25868853, 2015). "PCDH9 and CCND1 (Cyclin D1) exhibited a positive correlation, whereas MMP2, MMP9, and RAC1 exhibited a negative correlation with both melanoma A375 and G361 cells." (PMID 36452505, 2022). "d-GM3 containing melanoma cells possess increased migratory and invasive capacities, as compared to melanoma cells lacking d-GM3, thanks to the stimulation of MMP2 expression via the urokinase-like plasminogen activator receptor." (PMID 33121001, 2020). "A subsequent study from our group showed that MMP-2 and MMP-9 were not upregulated in invading melanoma cells but in the surrounding keratinocytes and fibroblasts." (PMID 27270229, 2016). "It is known that elimination of TFAP2A from non-metastatic primary melanoma cells increases their malignancy while re-expression abrogates it, by controlling transcription of genes such as MCAM-MUC18, MMP2, PAR1, VEGF, BCL2, CDKN1A/p21, E-cadherin and KIT." (PMID 25650662, 2015). "Due to that, we observed lower standard deviation and, thus, statistically significant differences in the level of MMP2, MMP14, RUNX2, or CD44 in CAFs obtained by incubation with conditioned media, but not by co-culturing with melanoma cells present on Transwell inserts." (PMID 35538545, 2022). "Melanoma and CRC cell migration was affected in a dose-dependent fashion as observed through scratch assay, whereas the secretion of matrix degrading proteins metalloprotease 2 (MMP2) and 9 (MMP9) in tumor cells did not significantly change." (PMID 36297277, 2022). "Although SIM exerts suppressive effects on expression and activation of MMPs52 and on melanoma cell migration capacity when co-administered with DMXAA9, our data suggested no significant modulation of MMP-2 and MMP-9 lytic activity by either LCL-SIM or LCL-DMXAA (P > 0.05)." (PMID 34764332, 2021).
melanoma (continued). "Moreover, fisetin treatment resulted in downregulation of MMP-2 and MMP-9 (data not shown) in monolayer and 3-D melanoma cultures (Sup." (PMID 30356079, 2018). "Whether or not a combination of MCAM, MMP-2, CCPG4, PAX-3, and Gal-3 can identify those thin melanomas that comprise the 5% that will develop metastases at a later stage will require further studies of clinical material." (PMID 24069584, 2013). "IL-8-transfected melanoma cells displayed greatly increased levels of MMP-2, while transfection of identical melanoma cells with VEGF and bFGF did not affect MMP-2 levels demonstrating that this is an important but separate mechanism involved in tumor-induced angiogeneses." (PMID 20445741, 2010). "Moreover, GAS5 attenuates the expression and the activity of MMP2 and MMP9 and has a role in regulating the metastasis phenotype of melanoma cells; however, no data are published about the role of GAS5 as a regulator of MMP9 and MMP2 expression in IBD patients." (PMID 31652976, 2019).